MPO (myeloperoxidase)
Diseases named in the same sentence as MPO in open-access papers (continued):
Sharing a sentence is not in itself a finding about the gene and the disease.
infarction (11 papers, 2013 to 2025). A localised pathological necrosis of tissue resulting from obstruction of the blood supply usually by a thrombus, an embolus, or vascular torsion. "Resveratrol significantly reduced the volume of cerebral infarcts and neurological damage scores in cerebral ischemia/reperfusion rats, significantly lowering levels of myeloperoxidase, TNF-α, and upregulating p-Akt expression." (PMID 40823184, 2025). "During the early phase (6–24 h post-infarction), neutrophil infiltration exacerbates myocardial injury through NETosis-mediated release of myeloperoxidase (MPO), amplifying oxidative stress." (PMID 41158309, 2025). "The result was also correspondent with previous study, which showed that HBO treatment might reduce local MPO activity, neutrophils infiltration, and infarction volume and thus enhance functional outcome for rats with focal ischemia." (PMID 23533308, 2013). "Thus, the estimation of MPO and MMP-8 elucidates not only the pathogenetic importance of NETosis but also provides notable contributions to the diagnosis of NSTEMI and the risk of necrotic zone expansion in the post-infarction evolution of the patient." (PMID 39351477, 2024). "In view of the close association between apoptosis and oxidative stress, we next detected the level of MPO, MDA, and 8-OHdG, the molecules relevant to oxidative stress, in penumbra around infarction areas at 90 min reperfusion." (PMID 34322032, 2021). "This was confirmed in Mpo−/− mice, which displayed retardation of fibrotic scar formation and an overall beneficial functional outcome after permanent LAD ligation induced MI; of note, MPO does not affect total infarction size." (PMID 33916434, 2021).
intestinal inflammation (11 papers, 2012 to 2024). "Previous findings have reported that EAEC detection was associated with higher levels of MPO (a marker for intestinal inflammation), NEO (intestinal inflammation), and AAT (permeability) among all 8 sites of MAL-ED32." (PMID 34848801, 2021). "DAI is composed of body weight change, diarrhea, and hematochezia and MPO is closely associated with inflammatory response and tissue damage in acute or chronic intestinal inflammation." (PMID 34683406, 2021). "Intestinal inflammation and specifically higher levels of fecal MPO, have been associated with poor linear growth among children in Brazil, Bangladesh, and the Gambia." (PMID 28742106, 2017). "Numerous biomarkers of EED measured in urine, blood, and stool have been proposed, including alpha-1-Antitrypsin (AAT) reflecting increased intestinal permeability and protein loss, calprotectin (CP) and myeloperoxidase (MPO) both reflective of the presence of intestinal inflammation." (PMID 38330085, 2024). "The intestinal anti-inflammatory activity of esculetin (25 mg/Kg by oral route) in mice DSS-induced intestinal inflammation model was related to a reduction in MPO activity, counteraction of GSH depletion, and reduction in IL-6 production." (PMID 37111267, 2023). "In the DSS-model of intestinal inflammation in mice osthole showed protective effects on intestinal inflammation improving clinical parameters and histological damages as well as reducing MPO activity and downregulating colon TNF-α and serum TNF-α levels." (PMID 33467396, 2021). "Accordingly, in the present study, we examined the protective effects of a PHL aqueous extract on TNBS-induced intestinal inflammation using a macroscopic score and histological analysis as well as by determination of the MPO activity and GSH content." (PMID 29853790, 2018). "The effects of the PHL extract on the MPO activity and GSH content in rats with TNBS-induced intestinal inflammation were examined using MPO and GSH assays." (PMID 29853790, 2018). "Daphnetin was reported as a potent intestinal anti-inflammatory coumarin derivative in the TNBS model of intestinal inflammation in rats, reducing gut damage lesions, MPO, and alkaline phosphatase activities, and counteracting GSH depletion when orally administered at doses of 2.5, 5, and 10 mg/Kg." (PMID 37111267, 2023). "Fecal myeloperoxidase (MPO) and neopterin (NEO) were markers of intestinal inflammation whereas plasma lipopolysaccharide-binding protein (LBP) and C-reactive protein (CRP) were assessed as markers of systemic inflammation." (PMID 39775265, 2024). "Similar to previously reported, 4-methylesculetin improved clinical, histopathological, and biochemical parameters, such as GSH levels and MPO activity in both acute and subchronic phases of the TNBS-induced intestinal inflammation model." (PMID 33467396, 2021). "In addition to the histological changes, MPO activities in the intestine were induced by 5-FU and suppressed by 5-ASA, also indicating that 5-FU induced intestinal inflammation, while 5-ASA suppressed 5-FU-induced inflammation." (PMID 22412841, 2012).
liver inflammation (11 papers, 2011 to 2025). "Liver inflammation was determined by detecting the secretion of pro-inflammatory cytokines and neutrophil infiltration through enzyme-linked immunosorbent assay (ELISA) and myeloperoxidase (MPO) immunohistochemistry staining." (PMID 33292377, 2020). "The results of histopathological changes, serum biochemical analysis, NO levels and myeloperoxidase activity showed that Baicalin pretreatment ameliorated LPS-induced liver inflammation." (PMID 28868036, 2017). "Studies have shown that TXNIP knockdown can upregulate the expression of tight junction protein ZO-1 and occluding in intestinal epithelial cells of mice with non-alcoholic steatohepatitis, reduce MPO activity and ROS levels, and reduce hepatitis-induced intestinal mucosal injury." (PMID 37530723, 2023). "Furthermore, SHK decreased the MPO level, which is usually indicative of the extent of liver inflammation." (PMID 30597971, 2018). "In the present study, GSE displayed an efficacy to protect against DEN-2AAF-induced liver inflammation by decreasing numbers of ED1- and ED2- positive macrophages and levels of hepatic MPO, a marker of neutrophil infiltration." (PMID 29352129, 2018). "The activity of MPO in the mice increased significantly after the APAP insult, leading to serious liver inflammation." (PMID 30116489, 2018).
nonalcoholic steatohepatitis (11 papers, 2012 to 2025). "Recent studies have also indicated that ABAH reduces MPO-dependent hepatocyte death in a non-alcoholic steatohepatitis model, decreases MPO activity in a mouse model of acute stroke, and inhibits MPO activity in sputum from pulmonary cystic fibrosis." (PMID 41209000, 2025). "Patients with non-alcoholic steatohepatitis had elevated serum MPO-DNA, and in a mice model of HCC, inhibition of NET formation decreased tumor growth." (PMID 34504150, 2021). "MPO is also associated with the development of non-alcoholic steatohepatitis (NASH) and MPO plasma levels and hepatic MPO activity have been reported to increase in patients with NASH26–28." (PMID 31822739, 2019). "In addition, green tea extract lowered pro-inflammatory genes such as iNOS, MCP-1, and MPO by regulation of NF-κB phosphorylation to protect against high-fat diet-induced nonalcoholic steatohepatitis." (PMID 39572022, 2024).
respiratory failure (11 papers, 2013 to 2026). The significant impairment of gas exchange within the lungs resulting in hypoxia, hypercarbia, or both, to the extent that organ tissue perfusion is severely compromised. "Here, we describe a 24-year-old woman from Medina, Saudi Arabia, who presented with life-threatening DAH and acute hypoxemic respiratory failure secondary to MPO-AAV." (PMID 42158806, 2026). "Surprisingly, the 1-year survival rate of our reviewed cases of GPS with pre-existing interstitial pneumonia and positive MPO-ANCA was 29%, and the cause of death in those cases was respiratory failure." (PMID 28403904, 2017). "MPO-ANCA patients were treated with CYC (15 mg/kg IV per biweekly dose) and in the case of the most severely ill patient requiring VV-ECMO because of prolonged DAH and profound respiratory failure, CYC was combined with RTX (1000 mg IV per dose, two weeks apart)." (PMID 39407748, 2024). "Besides, the groups of c/PR3-ANCA-positive and p/MPO-ANCA-positive patients were similar in terms of pulmonary arterial hypertension, pulmonary nodules, pulmonary infiltrates, pleural effusions, pulmonary embolism and respiratory failure." (PMID 34760903, 2021).
Splenomegaly (11 papers, 2015 to 2026). Abnormal increased size of the spleen. "Regarding the clinical features, most of the MPO+ve patients (87.5%) had B-symptoms, a half of them had associated lymphadenopathy and about 62.5% had splenomegaly at time of presentation." (PMID 34319037, 2021). "Besides, hematopoietic Znhit1 deficiency resulted in splenomegaly and disorganized splenic structure, which associated with myeloid cells infiltration and myeloperoxidase (MPO)-positive cells increase." (PMID 32694618, 2020). "Though a lower percentage of MPO-ve patients presented with B-symptoms (61.3%), higher percentages revealed lymphadenopathy and splenomegaly (59 and 70.4% respectively)." (PMID 34319037, 2021). "We also observed higher levels of MPO-DNA in patients with fever, arthralgia, skin rash, myalgia, lymphadenopathy, hepatomegaly, splenomegaly, and pericarditis." (PMID 33240258, 2020). "Also, increased serum elastase and myeloperoxidase (MPO) levels are detected in CVID patients with splenomegaly, a clinical feature more frequently observed in CVID patients with GLILD." (PMID 39431514, 2024). "Laboratory tests showed elevated platelet-associated IgG (PA-IgG), increased bone marrow megakaryocytes, negative antinuclear antibody, MPO-ANCA, anti-Helicobacter pylori antibody, and no splenomegaly, leading to a diagnosis of ITP." (PMID 41939544, 2026).
adenoma (10 papers, 2011 to 2025). A neoplasm arising from the epithelium. "Stool fibrinogen, MMP-8, MMP-9, PGRP-S, haptoglobin, and myeloperoxidase emerge as promising biomarkers for distinguishing CRC/advanced adenomas/healthy stools, meeting or outperforming current yardsticks." (PMID 41033463, 2025). "During the advanced adenoma (AA) stage, NETosis leads to reactive oxygen species (ROS) production, triggering MPO release, which further amplifies cellular damage and promotes tumor progression." (PMID 40003985, 2025). "MPO levels have also been found to be increased in colorectal mucosa of patients with adenoma or carcinoma." (PMID 22007198, 2011). "We found that DEFA4 is associated with non-advanced adenoma, MPO with advanced adenoma, and CD177 with CRC, suggesting their potential as biomarkers for distinct ACS stages." (PMID 40003985, 2025). "In the same study, CXCR2+ MPO+ (Myeloperoxidase) cells infiltrated spontaneous intestinal tumors in Apcmin/+ and AhCreER; Apcfl/+; Ptenfl/fl mice and CXCR1/2 blocking pepducin treatment suppressed tumor infiltration of MPO+ cells and adenoma formation concurrently." (PMID 38786066, 2024). "Qinghua Jianpi Recipe can significantly improve the intestinal inflammatory state of adenoma cancer model mice, reduce the number of 1-3 mm adenoma, reduce intestinal inflammatory activity and pathological intestinal damage, and reduce the expression of proinflammatory cytokine MPO in colon tissue." (PMID 36844438, 2023). "In addition, B. vulgatus showed positive correlation with inflammatory markers (i.e. myeloperoxidase and IL-1β levels), tumor numbers, and high-grade adenoma, especially, developed mucosal and submucosal invasive adenocarcinoma at the distal part of the colon." (PMID 34249773, 2021). "The upregulation of MPO and CD177, markers closely associated with neutrophil activity, supports the hypothesis that innate immune responses are a driving force in the transition from adenomas to carcinoma." (PMID 40003985, 2025). "Furthermore, the abundance of B. vulgatus was positively correlated with inflammatory markers (DAI score, and levels of MPO and IL-1β), developed tumor numbers, and high-grade adenoma developed mucosal and submucosal invasive adenocarcinoma, especially, at the distal part of the colon." (PMID 34249773, 2021). "This study highlights MPO and FCGR1A as particularly compelling biomarkers for both advanced adenoma detection and early CRC monitoring, addressing key clinical unmet needs in CRC diagnosis and prognosis." (PMID 40003985, 2025). "MPO, however, was significantly upregulated in the non-advanced and advanced adenoma groups, confirming its role as a circulating biomarker throughout the ACS." (PMID 40003985, 2025). "An RT-qPCR analysis was performed to validate FCGR1A and MPO levels in 20 samples, each from the advanced adenoma, non-advanced adenoma, and HC groups." (PMID 40003985, 2025). "Similarly, also adenomas displayed a specific enrichment in F4/80+ cells, but not in either MPO- or CD4-positive cells, thus possibly indicating that BRAFV600E-driven adenomas may preferentially recruit macrophages rather than neutrophils or lymphocytes." (PMID 35145078, 2022).
cognitive decline (10 papers, 2006 to 2025). "The MPO AA genotype, which decreases the production of myeloperoxidase, was associated with cognitive decline among older adults (aged 70–79 years)." (PMID 36873953, 2023). "A recent study showed that an MPO-deficient mouse model of AD was protected against cognitive decline." (PMID 32171317, 2020). "Next, we tested whether MPO deficiency would inhibit the cognitive decline seen in 5XFAD mice." (PMID 31611761, 2019). "Our results suggest that anserine protects elderly persons with MCI from cognitive declines by suppressing MPO-mediated neuroinflammatory responses." (PMID 33472172, 2021). "In this work, we show that MPO-deficient 5XFAD exhibit superior behavioral performance compared to MPO-expressing 5XFAD mice, thus reflecting limited cognitive decline." (PMID 31611761, 2019). "The results suggest that anserine may safeguard elderly individuals with MCI from cognitive decline by suppressing myeloperoxidase (MPO)-mediated neuroinflammatory responses." (PMID 38259497, 2023). "In animal models, neutrophil-derived MPO seems to be involved in the pathogenesis of Alzheimer’s like disease and inhibition of MPO might present a novel therapeutic target to combat cognitive decline." (PMID 35239655, 2022). "In addition, the profound protection against cognitive decline following MPO depletion may account for the reduced oxidative damage derived from neutrophils, which consider a substantial part of the pathology in AD." (PMID 31611761, 2019).
dementia (10 papers, 2021 to 2025). Loss of intellectual abilities interfering with an individual's social and occupational functions. "In patients with dementia (n = 202), only serum MPO-DNA was significantly higher in patients with delirium versus no delirium (0.255 versus 0.170 optical density, P = 0.044)." (PMID 39737468, 2025). "A study found R327H in the MPO protein after a comprehensive investigation in 38 patients with Dementia." (PMID 36011324, 2022). "In addition to CD14, CD40L, and MPO relate to the executive function neuropsychological testing domain; CD5L and sRAGE relate to global and regional MRI markers of brain atrophy; CD5L shows marginal association with dementia, and AD dementia." (PMID 36083988, 2022).
dermatitis (10 papers, 2010 to 2022). An inflammatory process affecting the skin. "To understand the therapeutic mechanism associated with KRO-105714 in these dermatitis models, we analyzed MPO and EPO activities, which are well-known for their critical roles in dermatitis." (PMID 32514255, 2020). "LCZ exhibited stronger inhibition of both the increase in KC and MIP‐2 content and MPO activity in the ear skin of mouse TPA‐induced dermatitis than did the other antifungal agents." (PMID 31724251, 2020). "The result of in vivo Imaging System at day 14 were in line with the degree of dermatitis scores, reflecting the degree of inflammation with MPO production due to the accumulation of activated neutrophils and macrophages." (PMID 29416104, 2018). "In the OXA-induced dermatitis model, we determined myeloperoxidase (MPO) activities as an indirect measurement of PMN infiltration, using noninvasive and highly sensitive bioluminescence imaging (BLI)." (PMID 26599340, 2015). "An important reduction of MPO activity was observed in a T-cells dependent model of skin inflammation (DNFB-induced CHS) by [44AANA47]-CCL5 at 1 mg/kg (46.6% (53.4% of vehicle)." (PMID 20090949, 2010). "As a result, KRO-105714 significantly reduced MPO activity in TPA-induced dermatitis tissues." (PMID 32514255, 2020). "It has been reported that intradermal injection of 1 μg of LPS causes a massive neutrophil swarm in mouse skin and preliminary experiments of this study showed that LPS injection resulted in a 2–3 fold increase of MPO activity and localized skin inflammation by 12 h post injection." (PMID 27936239, 2016). "The H&E sample for patient P7 exhibited lobular panniculitis with MPO+/CD15- mononuclear cell infiltration, in addition to superficial and deep perivascular dermatitis with interface vacuolar degeneration." (PMID 36211342, 2022). "In both the TPA and oxazolone induced dermatitis models, KRO-105714 reduced ear weights and MPO and EPO activity." (PMID 32514255, 2020). "These antifungal agents had different inhibitory effects on ear swelling, MPO activity, and KC and MIP‐2 contents in mouse TPA‐induced dermatitis." (PMID 31724251, 2020). "DNFB-induced dermatitis in NC/Nga (or NC.h2nc/nc), NC.h2b/b and NC.h2b/nc was evaluated by both a scoring index of AD19 and the myeloperoxidase (MPO) activity using in vivo Imaging System." (PMID 29416104, 2018). "Taken together with the significantly reduced levels of MPO activity at the site of inflammation, the data confirm the role of 15-epi-LXA4 as a promoter of the resolution of inflammation in the OXA-induced dermatitis model." (PMID 26599340, 2015). "The biological effects of 15-epi-LXA4 on the oxazolone (OXA)-induced skin inflammation model and on non-invasive, highly sensitive bioluminescence imaging (BLI) of myeloperoxidase (MPO) activitiy were also determined." (PMID 26599340, 2015).
neutropenia (10 papers, 2012 to 2024). A decrease in the number of neutrophils found in the blood. "Many drugs associated with IDIAG and neutropenia, particularly those containing electron-rich functional groups that contain nitrogen or sulfur, are oxidized by activated neutrophils, other myeloid cells, enzyme systems including myeloperoxidase, or simply by hypochlorous acid." (PMID 36674761, 2023). "She had intermittent neutropenia for more than 3 years; her BM exam revealed a low percentage of MPO-positive cells with MPO grade 1." (PMID 35525891, 2022). "The mechanism of neutropenia induction by tofacitinib is through the oxidation of tofacitinib to nitrenium ion by myeloperoxidase (MPO) in neutrophils, which reacts with sulfhydryl groups of cysteine residues of cellular proteins in leucocytes." (PMID 34790443, 2021). "The concentrations of tumor necrosis factor-α, interleukin (IL)-1β, IL-6 and myeloperoxidase in BAL fluid were significantly inhibited by imatinib or nilotinib in mice of ALI during neutropenia recovery." (PMID 23787115, 2013). "We found that the concentrations of TNF-α, IL-6, IL-1ß, and MPO were dramatically increased in BAL fluid after LPS administration during neutropenia recovery." (PMID 23787115, 2013). "MPO-positive cells ranged from 20 to 60% in the patients with acquired neutropenia." (PMID 35525891, 2022).